SRD5A1 (steroid 5 alpha-reductase 1)
Description:
Catalyzes the irreversible stereospecific reduction of the delta 4,5 bond (double bond between carbons 4 and 5) of various 3-oxo steroids (3-keto steroids) producing their 5alpha dihydro-3-oxo forms. Converts testosterone into 5-alpha-dihydrotestosterone (DHT), a more potent androgen as it is the preferred ligand for androgen receptor (AR) transactivation, making this reaction a key step in male sexual differentiation during development. Besides testosterone, it can also act on other steroids, including progesterone, androstenedione, and corticoids, producing metabolites with diverse roles. Hence, it plays a central role in sexual differentiation and androgen physiology.
Synonyms: S5AR 1
Tractability: Small molecule: an approved drug acts on it; a high-quality ligand is known; it belongs to a druggable protein family. Antibody: UniProt predicts a signal peptide or a membrane-spanning region. PROTAC: ubiquitination databases record sites on it; a small molecule that binds it is known.
Target class: Enzyme; Oxidoreductase
Chemical probes: CHEMBL118446
Gene: Protein-coding gene on chromosome 5 (6,633,290 to 6,676,539, forward strand). Ensembl gene ENSG00000145545.
Subcellular location: Microsome membrane; Endoplasmic reticulum membrane
Pathways (Reactome):
Metabolism: Androgen biosynthesis
Gene Ontology:
Molecular function: 3-oxo-5-alpha-steroid 4-dehydrogenase (NADP+) activity; 3-oxo-5-alpha-steroid 4-dehydrogenase activity; protein binding; electron transfer activity; NADPH binding; oxidoreductase activity, acting on the CH-CH group of donors
Biological process: androgen biosynthetic process; male gonad development; sex determination; androgen catabolic process; androgen metabolic process; bone development; cellular response to cAMP; cellular response to dexamethasone stimulus; cellular response to epinephrine stimulus; cellular response to estradiol stimulus; cellular response to growth factor stimulus; cellular response to insulin stimulus; cellular response to serotonin; cellular response to starvation; cellular response to testosterone stimulus; cerebral cortex development; diterpenoid metabolic process; female genitalia development; hippocampus development; hypothalamus development; lipid metabolic process; liver development; male genitalia development; pituitary gland development; progesterone metabolic process; and 14 more
Cellular component: endoplasmic reticulum membrane; neuronal cell body; cell body fiber; membrane; perinuclear region of cytoplasm
Genetic constraint (gnomAD): Loss-of-function variants: 17 observed, 20.02 expected, observed/expected ratio (o/e) 0.85, 90% interval 0.58 to 1.27. The synonymous counts are far from expectation, so gnomAD's model fits this gene poorly and the ratio says little. Missense variants: 274 observed, 283.14 expected, observed/expected ratio (o/e) 0.97, 90% interval 0.88 to 1.07. Synonymous variants: 139 observed, 109.2 expected, observed/expected ratio (o/e) 1.27, 90% interval 1.11 to 1.47.
Homologues: Orthologues: chimpanzee SRD5A1 (100% identical), macaque SRD5A1 (93% identical), dog SRD5A1 (71% identical), rabbit SRD5A1 (68% identical), guinea pig SRD5A1 (65% identical), pig SRD5A1 (63% identical), mouse Srd5a1 (61% identical), rat Srd5a1 (60% identical), zebrafish srd5a1 (53% identical), tropical clawed frog srd5a1 (50% identical), Caenorhabditis elegans F42F12.3 (37% identical), Caenorhabditis elegans F19H6.4 (37% identical), and 1 more. Paralogues in human: SRD5A2 (46% identical), TECR (24% identical), TECRL (19% identical).
Diseases named in the same sentence as SRD5A1 in open-access papers:
SRD5A1 is named in the same sentence as 50 diseases in open-access papers, as found by Europe PMC text mining. Sharing a sentence is not in itself a finding about the gene and the disease. The quoted sentences say what the papers report.
prostate carcinoma (11 papers, 2011 to 2025). A carcinoma that arises from epithelial cells of the prostate gland. "Elevated levels of SRD5A1 and SRD5A2 have been reported in prostate cancer and a correlation with the severity of the disease linked to increased dihydrotestosterone levels was documented." (PMID 22257483, 2012). "Also, in both human prostate cancer (DU-145) and HFDPC cells, the ethanolic Buebang 3 CMU extract (Et-BB3-CMU) suppressed SRD5A1, SRD5A2, and SRD5A3 expression—key pathways in hair loss—by 2-fold and 1.5-fold more than minoxidil and finasteride, respectively." (PMID 39519997, 2024). "Elevated levels of SRD5A1 have been reported to be correlated to the severity of multiple cancers with their nidus situated to the parts rich in sex hormone, including prostate cancer, breast cancer, endometrial cancer, or the like, and to facilitate cell proliferation." (PMID 33627630, 2021). "Besides in NSCLC, over-expression of SRD5A1 was observed in breast cancer, and also in ovary, cervix and prostate cancer." (PMID 22257483, 2012). "Type I and III of SRD5A coexist in prostate cancer cells to boost the AR pathway and support prostate cancer initiation and progression, thus downregulating either SRD5A1 or SRD5A3 may restrict the AR pathway and further inhibit the growth of prostate cancer cells." (PMID 37152995, 2023). "Increased levels and activity of SRD5A1 in prostate cancer result in high DHT levels and castration-resistant prostate cancer." (PMID 39764142, 2024). "In human prostate cancer cells (DU-145) and HFDPC cells, the SFE-4 extract significantly decreased the expression of SRD5A1, SRD5A2, and SRD5A3, an essential pathway involved in AGA." (PMID 38002174, 2023). "After various treatment regimes, fluorescent microscopy was performed to visualize the subcellular localization of immunofluorescence-tagged SRD5A1 and SRD5A3 in the prostate cancer PC-3 and LNCap cell lines." (PMID 37152995, 2023). "Type I and type III 5α-reductase (SRD5A1 and SRD5A3) were discovered to be correlated with DHT generation and AR activation in malignant prostate tumors, while type II (SRD5A2) is primarily expressed in normal prostate tissues." (PMID 37152995, 2023). "Immunohistochemical and polymerase chain reaction (PCR) analyses of human prostate tissues suggest that SRD5A1 and SRD5A2 levels change with prostate cancer development and progression." (PMID 22194926, 2011). "Our qRT-PCR analysis showed that DHT treatment resulted in an increased level of SRD5A1 mRNA, whereas it led to decreased levels of SRD5A2 and SRD5A3 mRNA in LNCaP prostate cancer cells." (PMID 22194926, 2011). "SRD5A1 and SRD5A3 were the primary isozymes in the prostate cancer cells, and suppression of SRD5A1 and SRD5A3 protein levels was reported to be a promising alternative therapy to block the AR signaling pathway and inhibit the growth of malignant prostate tumors." (PMID 37152995, 2023). "We speculate, based on our findings and studies in prostate cancer, that ADT response in SRD5A1 overexpressing tumors may be further enhanced by adding the SRD5A1 inhibitor dutasteride to the ADT regimen." (PMID 31745978, 2020). "Over-expression of SRD5A1 and SRD5A2 has been noted in breast and prostate cancer samples." (PMID 22257483, 2012).
breast carcinoma (7 papers, 2011 to 2024). "A stimulatory effect of E2 on Srd5a1 expression has been reported in human breast cancer cell lines, mediated though ESR1 binding to an upstream distal enhancer, tethered via additional proteins." (PMID 37646011, 2023). "Expression of SRD5A1 was also detected in many different human cell lines on the Array Northern (Affymetrix HGU133Plus2.0 array), with highest levels observed in breast cancer cells." (PMID 22257483, 2012). "Indeed, we found SRD5A1 to be markedly elevated in prostate and breast cancer, and also in several breast cancer cell lines." (PMID 22257483, 2012). "SRD5A1 and SRD5A2 are also consistently over-expressed in breast cancer, which increases the levels of progesterone metabolites possibly involved in cell proliferation." (PMID 22257483, 2012). "SRD5A1, a member of the steroid 5α-reductase family (SRD5A1, SRD5A2, and SRD5A3) converting testosterone to dihydrotestosterone (DHT), was recently reported to be aberrantly expressed in several sex hormone-related cancers, such as breast cancer, endometrial cancer, and prostate cancer." (PMID 33627630, 2021). "This include the Steroid 5-alpha-reductase SRD5A1, the CCR4-NOT component RQCD1 and the Rab11 effector protein RAB11FIP1 which have all been reported as up-regulated in breast cancers." (PMID 22691140, 2012). "In patients with breast cancer, the negative correlation between methylation and ESR1 induction of gene expression involved mostly CpGs located at enhancers >1 kbp downstream of the transcription start site, corresponding with the location of the intronic enhancer of Srd5a1." (PMID 37646011, 2023).
benign prostatic hyperplasia (5 papers, 2017 to 2024). A non-cancerous nodular enlargement of the prostate gland. "This conversion can be inhibited by dutasteride, a potent SRD5A1-inhibitor, which is currently prescribed for benign prostatic hyperplasia." (PMID 39304797, 2024). "Current research has been focused on a relationship between the disease severity and AR regulatory pathway mediated by SRD5A1 overexpression in benign prostatic hyperplasia and PC." (PMID 32983992, 2020). "Among these genes, steroid 5α-reductase 1 (SRD5A1) and steroid 5α-reductase 2 (SRD5A2) encode 5α-reductase type 1 and type 2, respectively, which are involved in testosterone metabolism and have been associated with an increased risk of prostatic hyperplasia." (PMID 38778357, 2024).
alopecia (2 papers, 2025 to 2026). Hair loss usually from the scalp. "Here, we analyzed the gene expression of the two main 5α-reductases associated with hair loss, SRD5A1 and SRD5A3." (PMID 40286110, 2025).
Hepatic steatosis (2 papers, 2016 to 2021). Steatosis is a term used to denote lipid accumulation within hepatocytes. "At the same time congenital deficiency of SRD5A1 causes intrahepatic accumulation of glucocorticoids and induces IR, hepatic steatosis and even fibrosis." (PMID 34764940, 2021). "SRD5A1 knockout mice develop hepatic steatosis when fed an obesogenic diet, whereas SRD5A2 knockout mice do not." (PMID 26574953, 2016).
hypospadias (2 papers, 2013 to 2020). Hypospadias is the displacement of the urethral meatus on the ventrum of the penis. "Among the OMIM genes in their overlapping deleted region, haploinsufficiency of SRD5A1 has been implicated as a candidate genetic reason for hypospadias." (PMID 32500674, 2020).
lung carcinoma (2 papers, 2012 to 2024). "High expression of SRD5A1 expression was furthermore measured in the lung cancer cell lines A549 and NCI-H460." (PMID 22257483, 2012). "In addition, lung cancer cell lines were treated with 4-azasteroids, which specifically inhibit SRD5A1 activity, and the effects on proliferation were measured." (PMID 22257483, 2012). "A study was therefore initiated to determine whether SRD5A1 played a determinant role in lung cancer cell proliferation." (PMID 22257483, 2012). "siRNA-mediated silencing of SRD5A1 was performed in A549 and NCI-H460 lung cancer cell lines in order to determine the impact on proliferation, on distribution during the different phases of the cell cycle, and on apoptosis/necrosis." (PMID 22257483, 2012). "A total of 83 potential targets of ROB in lung cancer were collected and further screened by using Cytoscape software, and 7 targets of PTGS2, CYP19A1, PTGS1, AR, CYP17A1, PTGES and SRD5A1 were obtained as hub genes and 7 hub targets had good binding energy with ROB." (PMID 39450260, 2024). "On the other hand, it cannot be excluded that the conditions used here did not allow the proper assessment of the role of SRD5A1 in lung cancer." (PMID 22257483, 2012). "The hub targets of ROB action in lung cancer were further analyzed by combining 14 targets from Degree≥6, 10 targets each from MCC and MNC algorithms, and finally 7 common targets such as PTGS2, CYP19A1, PTGS1, AR, CYP17A1, PTGES and SRD5A1 were obtained from the final screening." (PMID 39450260, 2024).
metastatic prostate carcinoma (2 papers, 2022 to 2023). A carcinoma that arises from the prostate gland and has spread to other anatomic sites. "The down-regulated expression level of AKR1C2 combined with upregulated expression of SRD5A1 and SRD5A3 may lead to the high levels of DHT either in primary or metastatic prostate cancer." (PMID 36701414, 2023). "Increases in oncogenic AR activity may be driven by somatic changes that upregulate crucial APUC genes in the metastatic prostate cancer tumors, such as HSD3B2 (1.8-fold increase) and SRD5A1 (2.1-fold increase)." (PMID 37435458, 2022).
non-small cell lung carcinoma (2 papers, 2012 to 2020). A group of at least three distinct histological types of lung cancer, including non-small cell squamous cell carcinoma, adenocarcinoma, and large cell carcinoma. "Previous research has reported that SRD5A1 is highly expressed in prostate cancer (PC), breast cancer, non-small cell lung cancer, and liver cancer." (PMID 32983992, 2020). "However, the conclusion inferred from the research on non-small cell lung cancer remains evidently confirmatory, according to the fact that overexpression of SRD5A1 did not impact proliferation, cell cycle distribution, or apoptosis." (PMID 32983992, 2020).
polycystic ovary syndrome (2 papers, 2011 to 2024). A disorder that manifests as multiple cysts on the ovaries. "Interestingly, genetic variants in the Srd5a1 gene have been associated with two androgen linked conditions, polycystic ovary syndrome and hirsutism, in females." (PMID 21731732, 2011). "One of the conducted toxicogenomic studies which assessed the link between PFAS mixtures and polycystic ovary syndrome (PCOS) found 74 genes linked to both PFAS exposure and PCOS, highlighting cell cycle regulation and steroid hormone synthesis—particularly genes like CCNB1 and SRD5A1." (PMID 39596398, 2024).
Adrenal insufficiency (1 paper, 2014). Insufficient production of steroid hormones (primarily cortisol) by the adrenal glands. "We tested, in a mouse model, whether deficiency of 5α-reductase 1 (Srd5a1) activity causes relative adrenal insufficiency." (PMID 24872577, 2014).
alcohol dependence (1 paper, 2012). Physical and psychological dependence on alcohol. "Rs472402 is also in strong LD with rs248793 (r2 = 0.89), which has been associated with differences in SRD5A1 activity and with risk for alcohol dependence." (PMID 22952603, 2012).
androgenic alopecia (1 paper, 2022). "HaCaTs produced SRD5A1 as a major isozyme, which facilitates the use of a HaCaT cell-based assay for the screening of SRD5A1 inhibitor for androgenic alopecia." (PMID 36460729, 2022). "Both male and female patients with androgenic alopecia have high levels of SRD5A1 and SRD5A2 in frontal and occipital hair follicles." (PMID 36460729, 2022). "Thus, compound 4 shows the potential for further development as an SRD5A1 suppressor for androgenic alopecia treatment." (PMID 36460729, 2022). "Therefore, SRD5A1 serves as a crucial target for the treatment of androgenic alopecia by using the orally administered drugs, finasteride and dutasteride." (PMID 36460729, 2022). "Thus, the 3,4-dihydroxycinnamic motif could be studied for its structure–activity relationship against SRD5A1 inhibition to identify candidates for treatment of androgenic alopecia." (PMID 36460729, 2022). "Therefore, compound 4 is a promising non-steroidal SRD5A1 suppressor and should be further investigated in the clinical development stage for treating androgenic alopecia." (PMID 36460729, 2022).
bladder cancer (1 paper, 2023). "Also, we found SRD5A1 and its positively correlated genes were related with cell cycle, DNA replication, and mitosis from various bladder cancer datasets in R2 and Enrichr databases." (PMID 36800968, 2023).
cartilaginous tumours (1 paper, 2009). "Diffuse expression of SRD5A1 and sex steroid signalling-related molecules confirms the role of this pathway in cartilaginous tumours." (PMID 19903358, 2009).
Cerebellar hypoplasia (1 paper, 2013). Cerebellar hypoplasia is a descriptive term implying a cerebellum with a reduced volume, but a normal shape and is stable over time. "Only SRD5A1 haploinsufficiency has been speculated to be associated with cerebellar hypoplasia, hypospadias, and facial dysmorphisms in a prenatal study." (PMID 24143197, 2013).
chondroblastoma (1 paper, 2009). A benign, chondroid-producing, well-circumscribed, lytic neoplasm usually arising from the epiphysis of long bones. "Diffuse expression of the SRD5A1 protein, as identified by immunohistochemistry, was found in the index case as well as in the other chondroblastomas (13/13 tested)." (PMID 19903358, 2009). "However, diffuse expression of SRD5A1, ESR1 and CYP19 in all the chondroblastomas tested, including the index case, was found." (PMID 19903358, 2009).
cocaine dependence (1 paper, 2012). A psychologically and socially impaired state, with or without physiological changes, that develops as a result of using cocaine and which leads to compulsive behaviors to acquire the substance. "Finally, SRD5A1 has also been suggested as a positional candidate gene based on a linkage study for cocaine dependence and major depressive episode." (PMID 22952603, 2012).
depression (1 paper, 2023). "The 5α-reductase type I (SRD5A1), a steroidogenic hub enzyme involved in pregnenolone metabolism, was increased in the hypothalamus of female mice with depression." (PMID 38062440, 2023). "In addition, we observed SRD5A1 upregulation in the hypothalamus of female mice with depression after pregnenolone administration." (PMID 38062440, 2023). "Likewise, inhibition of SRD5A1, which decreases pregnenolone consumption, resulted in elevated levels of hypothalamic pregnenolone and improved depressive-like behaviors in female mice with depression." (PMID 38062440, 2023).
endometrial tumors (1 paper, 2016). "Analysis of the Cancer Genome Atlas (TCGA) database of endometrial tumors identified an inverse correlation between PR and Myc mRNA levels, with a corresponding inverse correlation between PR and Myc downstream transcriptional targets SRD5A1, CDK2 and CCNB1." (PMID 26859414, 2016).
Hepatic fibrosis (1 paper, 2016). The presence of excessive fibrous connective tissue in the liver. "Furthermore, in a model of hepatic fibrosis, SRD5A1 knockout animals developed more severe fibrotic liver disease." (PMID 26574953, 2016).
Insulin resistance (1 paper, 2015). Increased resistance towards insulin, that is, diminished effectiveness of insulin in reducing blood glucose levels. "In a recently published clinical study, nonselective 5α-reductase inhibition with dutasteride was associated with peripheral insulin resistance and it has been suggested that this may reflect a specific role for SRD5A1 in skeletal muscle." (PMID 25974403, 2015).
lymph node metastasis (1 paper, 2020). "Data showed that overexpression of SRD5A1 was remarkably related to pathological grade (χ2 = 9.044, P = 0.004), lymph node metastasis (χ2 = 9.873, P = 0.002), distant metastasis (χ2 = 5.953, P = 0.021), and survival status (χ2 = 6.787, P = 0.034)." (PMID 32983992, 2020). "Furthermore, clinical results showed that SRD5A1 is closely related to lymph node metastasis and distant metastasis." (PMID 32983992, 2020).
monoclonal gammopathy of undetermined significance (1 paper, 2021). "The expression of SRD5A1 was significantly increased successively from normal people (NP), monoclonal gammopathy of undetermined significance (MGUS) to MM patients." (PMID 33627630, 2021).